RNF111 (ring finger protein 111)
Description:
E3 ubiquitin-protein ligase. Required for mesoderm patterning during embryonic development (By similarity). Acts as an enhancer of the transcriptional responses of the SMAD2/SMAD3 effectors, which are activated downstream of BMP. Acts by mediating ubiquitination and degradation of SMAD inhibitors such as SMAD7, inducing their proteasomal degradation and thereby enhancing the transcriptional activity of TGF-beta and BMP. In addition to enhance transcription of SMAD2/SMAD3 effectors, also regulates their turnover by mediating their ubiquitination and subsequent degradation, coupling their activation with degradation, thereby ensuring that only effectors 'in use' are degraded (By similarity). Activates SMAD3/SMAD4-dependent transcription by triggering signal-induced degradation of SNON isoform of SKIL. Associates with UBE2D2 as an E2 enzyme. Specifically binds polysumoylated chains via SUMO interaction motifs (SIMs) and mediates ubiquitination of sumoylated substrates. Catalyzes 'Lys-63'-linked ubiquitination of sumoylated XPC in response to UV irradiation, promoting nucleotide excision repair. Mediates ubiquitination and degradation of sumoylated PML (By similarity). The regulation of the BMP-SMAD signaling is however independent of sumoylation and is not dependent of SUMO interaction motifs (SIMs) (By similarity).
Synonyms: hRNF111; ARK; Arkadia; FLJ38008; DKFZP761D081
Tractability: PROTAC: UniProt records ubiquitination sites on it; ubiquitination databases record sites on it.
Gene: Protein-coding gene on chromosome 15 (58,865,175 to 59,097,419, forward strand). Ensembl gene ENSG00000157450.
Subcellular location: Nucleus; Cytoplasm; Nucleus, PML body
Subcellular location (Human Protein Atlas): Nucleoplasm; Cytosol
Pathways (Reactome):
Signal Transduction: Downregulation of SMAD2/3:SMAD4 transcriptional activity; SMAD2/SMAD3:SMAD4 heterotrimer regulates transcription
DNA Repair: Formation of Incision Complex in GG-NER
Immune System: Antigen processing: Ubiquitination & Proteasome degradation
Gene Ontology:
Molecular function: protein binding; SUMO polymer binding; ubiquitin protein ligase activity; SMAD binding
Biological process: protein ubiquitination; global genome nucleotide-excision repair; positive regulation of transforming growth factor beta receptor signaling pathway; ubiquitin-dependent protein catabolic process
Cellular component: cytoplasm; cytosol; nucleoplasm; nucleus; PML body
Genetic constraint (gnomAD): Loss-of-function variants: 15 observed, 70.51 expected, observed/expected ratio (o/e) 0.21, 90% interval 0.14 to 0.33. The upper end of that interval is the gene's LOEUF score, 0.33, which puts it in group 1 of 6, group 1 being the genes least tolerant of losing a copy. Missense variants: 1,071 observed, 1,082.7 expected, observed/expected ratio (o/e) 0.99, 90% interval 0.94 to 1.04. Synonymous variants: 392 observed, 379.84 expected, observed/expected ratio (o/e) 1.03, 90% interval 0.95 to 1.12.
Homologues: Orthologues: chimpanzee RNF111 (99% identical), macaque RNF111 (99% identical), dog RNF111 (97% identical), pig RNF111 (96% identical), rabbit RNF111 (96% identical), guinea pig RNF111 (92% identical), rat Rnf111 (90% identical), mouse Rnf111 (90% identical), tropical clawed frog rnf111 (73% identical), zebrafish rnf111 (58% identical), Drosophila melanogaster CG6923 (16% identical), Caenorhabditis elegans toe-4 (15% identical). Paralogues in human: ARK2C (17% identical), ARK2N (11% identical).
Diseases named in the same sentence as RNF111 in open-access papers:
RNF111 is named in the same sentence as 13 diseases in open-access papers, as found by Europe PMC text mining. Sharing a sentence is not in itself a finding about the gene and the disease. The quoted sentences say what the papers report.
breast cancer (5 papers, 2021 to 2024). A primary or metastatic malignant neoplasm involving the breast. "Other studies have shown that the expression of circ-RNF111 is increased in paclitaxel-resistant tissues and cells, and knocking out circ-RNF111 reduces paclitaxel’s effectiveness on breast cancer cells." (PMID 39713143, 2024). "To validate these results, we demonstrated that knockdown of RNF111 or UBR5 rescued ER degradation by basic amino or acrylic acid SERDs, respectively, in reporter assays and of endogenously expressed ER in breast cancer cells." (PMID 37478846, 2023). "As reported, circ-ring finger protein 111 (circ-RNF111) and circ-ABCB10 enhanced PTX resistance in breast cancer." (PMID 34649611, 2021). "Similar to RNF12, RNF111/ARKADIA, was shown to promote cell migration and metastasis in breast cancer cells but also lung cancer cells." (PMID 33418880, 2021). "Notably, upregulation of mir-140-5p or suppression of E2F3 or Circ-RNF111 could reduce IC50, cell viability, colony numbers, cell invasion, and glycolysis of paclitaxel-resistant breast cancer lines." (PMID 36132137, 2022).
gastric cancer (4 papers, 2021 to 2025). A primary or metastatic malignant neoplasm involving the stomach. "Circ-RNF111 aggravates gastric cancer malignancy through mir-876-3p-dependent KLF12 regulation." (PMID 40426921, 2025). "For instance, circRNA RNF111 is the ceRNA for miR-27b to promote gastric cancer proliferation." (PMID 33896797, 2021).
lung carcinoma (3 papers, 2021). "Mutations that disrupt the C-terminal RING domain of RNF111 can occur in cancer, and we have shown that the NCI-H460 lung cancer cell line exhibits a S432∗ nonsense mutation that leads to the expression of a truncated form of RNF111 lacking its C-terminal RING domain." (PMID 34740826, 2021).
colorectal cancer (2 papers, 2012 to 2016). A primary or metastatic malignant neoplasm that affects the colon or rectum. "RNF111 acts as a tumour suppressor in preventing development and progression of colorectal cancer." (PMID 27829003, 2016).
chronic lymphocytic leukemia (1 paper, 2024). "These auto-Abs were against ACAN, a known biomarker in RA and ZMYM3 and RNF111, implicated in chronic lymphocytic leukemia and cancers, respectively." (PMID 38470480, 2024).
Hepatic fibrosis (1 paper, 2021). The presence of excessive fibrous connective tissue in the liver. "The RNF111 protein contents and the mRNA contents were remarkably different in fibrotic liver samples in contrast with in non-fibrotic liver samples, indicating that RNF111 has a core role in the pathogenesis and progress of hepatic fibrosis." (PMID 34485272, 2021).
leukemia (1 paper, 2023). A malignant (clonal) hematologic disorder, involving hematopoietic stem cells and characterized by the presence of primitive or atypical myeloid or lymphoid cells in the bone marrow and the blood. "The E3 ligase Arkadia (RNF111) targets for proteasomal degradation negative regulators of the TGF-β SMAD2/3 signaling pathway and poly-SUMOylated proteins, e.g., promyelocytic leukemia protein." (PMID 36831384, 2023).
osteosarcoma (1 paper, 2021). A usually aggressive malignant bone-forming mesenchymal neoplasm, predominantly affecting adolescents and young adults. "In order to profile the substrates of RNF111, we have generated U2OS osteosarcoma CRISPR modified cell lines that express a truncated form of RNF111 devoid of the C-terminal RING domain (RNF111-RING-KO) that mimics the truncation observed in the cancer cell line NCI-H460." (PMID 34740826, 2021). "Considering the role of RNF111 in both TGF-β signaling and DNA repair, we set our study in the U2OS osteosarcoma cell line that exhibits an intact functional response to both TGF-β and DNA damage." (PMID 34740826, 2021).
cancer (5 papers, 2021 to 2025). A tumor composed of atypical neoplastic, often pleomorphic cells that invade other tissues. "In humans, has_circ_0001982 (circRNA-RNF111) derived from the second exon of the ring finger protein 111 gene (RNF111) is reportedly involved in various cancers." (PMID 36377797, 2023). "To identify endogenous substrates of RNF111 E3 ubiquitin ligase function, we generated CRISPR engineered cell lines devoid of RNF111 RING domain by mimicking the stop mutation S432∗ observed on exon 5 of the RNF111 gene in the NCI-H460 carcinoma cell line." (PMID 34740826, 2021). "Truncations of the RING C-terminal domain of RNF111 that abolish its E3 function and subsequently activate TGF-β signaling are observed in some cancers." (PMID 34740826, 2021).
tumor (4 papers, 2016 to 2024). "Circ-RNF111 is highly expressed in GC cells and tissues, and tumor growth in vivo is inhibited when the Circ-RNF111 gene is knocked down." (PMID 39816354, 2024). "Our results presented that tumor size and tumor weight were inhibited after circ-RNF111 knockdown compared to sh-NC control groups." (PMID 34461926, 2021). "It was demonstrated that circ-RNF111 silencing restrained tumor formation in vivo." (PMID 34461926, 2021). "At last, the functional role of circ-RNF111 in tumor progression in vivo was explored." (PMID 34461926, 2021). "RNF111 was considered to have tumor suppressive activity, our study implied that it might partially be attributable to its neddylation modification of cGAS to facilitate immune responses." (PMID 33720974, 2021). "Besides, circ-RNF111 knockdown inhibited tumor growth in vivo." (PMID 34461926, 2021). "Moreover, circ-RNF111/miR-876-3p/KLF12 axis could deteriorate the progression of GC by triggering tumor cell growth, metastasis, and glycolysis and curbing apoptosis." (PMID 34461926, 2021).
RNF111 also shares sentences with these, for which no sentence is quoted: infection (1 paper); promyelocytic leukemia (1); xeroderma pigmentosum (1).